RNU6-133P (RNA, U6 small nuclear 133, pseudogene)
Gene: Small nuclear RNA gene on chromosome X (21,214,637 to 21,214,743, forward strand). Ensembl gene ENSG00000206716.
Homologues: Orthologues: chimpanzee U6 (97% identical), macaque U6 (94% identical), pig U6 (78% identical). Paralogues in human: RNU6-1067P (87% identical), RNU6-1145P (87% identical), RNU6-1181P (86% identical), RNU6-12P (86% identical), RNU6-13P (86% identical), RNU6-16P (86% identical), RNU6-32P (86% identical), RNU6-393P (86% identical), RNU6-41P (86% identical), RNU6-945P (86% identical), RNU6-968P (86% identical), RNU6-1 (85% identical), and 1285 more.